LOX (lysyl oxidase)
Diseases named in the same sentence as LOX in open-access papers (continued):
Sharing a sentence is not in itself a finding about the gene and the disease.
keratoconus (continued). "LOX and TIMP3 play a pivotal role in extracellular matrix maturation and remodeling, respectively, two process that could influence the loss of corneal structural components, leading to corneal thinning typical of keratoconus." (PMID 21976959, 2011). "Another recent multi-omics analysis reported methylation changes in LOX, SMAD3, KLF5, HOXB1, and BANP among others in keratoconus tissue." (PMID 41595486, 2026). "As for genetic factors, alterations in Lysyl oxidase (LOX), Collagen Type V Alpha 1 Chain (COL5A1), and Forkhead box protein O1 (FOXO1) gene have been correlated to keratoconus pathogenesis." (PMID 35054085, 2022). "LOX and SPARC are localized on chromosome 5q23.2 and 5q31.3-q32, respectively, in regions that show a suggestive linkage in familial keratoconus and thus are both indicated as possible candidate genes for keratoconus." (PMID 21976959, 2011). "In addition, a summary of the roles of both LOX and LOX-PP in diabetic retinopathy, and brief mentions of the roles for LOX and closely related LOXL1 in glaucoma, and keratoconus, respectively, are included." (PMID 35563478, 2022). "Therefore, accumulated information about these markers should be considered for application in diagnosis e.g., elevated MMP9 and IL6 along with a reduction in markers such as LOX, SFRP1 in tears can give a specific diagnosis of keratoconus." (PMID 27493978, 2016). "Nine studies were excluded since they focused on the biological activity of LOX rather than its genetic contribution to keratoconus." (PMID 26713757, 2015).
atherosclerosis (20 papers, 2011 to 2025). A disease characterized by the build-up of fatty material and calcium deposition in the arterial wall resulting in partial or complete occlusion of the arterial lumen. "Previous research showed that a feed-forward loop involving extracellular matrix deposition and LOX-dependent collagen crosslinking promotes atherosclerosis progression in hyperlipidemic, ApoE-deficient mice." (PMID 39143955, 2024). "Semicarbazide-sensitive amine oxidase (SSAO) and lysyl oxidase (LOX) are vascular enzymes associated with the development of atherosclerosis." (PMID 36358914, 2022). "Dysregulated LOX activity may play significant roles in cardiovascular diseases such as atherosclerosis and aneurysms, which are mediated by cross-linked structural ECM proteins." (PMID 34393991, 2021). "This could be due to down-regulation of Lysyl oxidase enzyme that is essential to maintain the tensile and elastic features of blood vessels and its deficiency has been implicated in atherosclerosis, fragmentation of elastic fibers, and alterations in endothelial cell functions." (PMID 36482036, 2023). "LOX is upregulated in human-calcified atherosclerotic lesions and atheromas from atherosclerosis-challenged LOX transgenic mice (TgLOXVSMC) and colocalized with a marker of oxidative stress (8-oxo-deoxyguanosine) in vascular smooth muscle cells (VSMCs)." (PMID 38790628, 2024). "Lysyl oxidase (LOX)-mediated extracellular matrix crosslinking modulates calcification in atherosclerosis and aortic valve disease; however, this enzyme also induces oxidative stress." (PMID 38790628, 2024). "Recently, we have shown that lysyl oxidase (LOX)-dependent collagen crosslinking drives osteogenic transdifferentiation and modulates mineralization in atherosclerosis and CAVD." (PMID 38790628, 2024). "Previously, we demonstrated SSAO to be closely associated with another vascular enzyme, lysyl oxidase (LOX), whose alterations in activity and expression have been linked with the early developing stages of atherosclerosis." (PMID 36902376, 2023). "Apart from its role in maintaining ECM stability, LOX dysregulation is involved in every phase of atherosclerosis." (PMID 36292250, 2022). "Our current knowledge regarding the role of LOX in the formation, progression, and vulnerability of atherosclerosis plaque is limited and is mostly derived from in vitro studies." (PMID 36142876, 2022). "For instance, elevated activity or increased expression of LOX can result in atherosclerosis and scleroderma, and the decreased expression of LOX and LOXL1/3 can lead to pelvic organ prolapse and keratosis." (PMID 36293126, 2022). "By contrast, in advanced atherosclerosis induced in rabbits fed an atherogenic diet, LOX activity significantly increased, particularly in the aortic arch." (PMID 31615160, 2019). "LOX dysregulation seems also to be involved in other vascular pathologies related with atherosclerosis, but mainly characterized by an intense destructuration of ECM such as aneurysms and artery dissections." (PMID 31615160, 2019). "Aberrant expression or activation of LOX alters the cellular microenvironment, leading to many diseases, including atherosclerosis, tissue fibrosis, and cancer." (PMID 28036074, 2016). "Elevated LOX activity has been shown to induce atherosclerosis and inhibition has led to plaque instability as reviewed by Rodriguez." (PMID 25875748, 2015). "In a pre-clinical disease model of atherosclerosis, 12/15 LOX knockout mice displayed increased atherosclerosis as compared to wild type." (PMID 21935407, 2011). "Early studies in chickens and pigs exhibited variable effects of dietary interventions on LOX activity, whereas in rabbits with advanced atherosclerosis and ApoE-deficient mice on a high-fat diet, LOX activity was elevated, and BAPN treatment ameliorated atherosclerosis." (PMID 40661776, 2025).
atherosclerosis (continued). "Atherosclerosis and calcification were induced in both transgenic mice that overexpress LOX in VSMCs (TgLOXVSMC) and their wild-type littermates (WT) using a single injection of an AAV encoding for PCSK9D374Y combined with an HF/HC diet for 20 weeks, as described." (PMID 38790628, 2024). "Given that cigarette smoking is implicated in L5–LOX-1 signaling pathway-related atherosclerosis and that smoking cessation could reduce an independent ASCVD risk marker (i.e., the LOX index), smoking cessation should be a priority." (PMID 34066436, 2021). "The experimental findings summarized in this review evidence the key contribution of LOX and LOXLs to multiple aspects of cardiovascular homeostasis, which could be relevant for the development of high-incidence human diseases such as atherosclerosis, HF, arterial aneurysms and aortic dissection." (PMID 31615160, 2019). "The knowledge on the role of LOX in the onset, progression, and instability of atherosclerotic plaque has been hampered by the lack of studies on this subject in humans, but different approaches in animal models support the contribution of LOX in atherosclerosis." (PMID 31615160, 2019). "LOX is also a source of vascular oxidative stress; however, whether LOX activity could contribute to the high ROS production in vascular calcification associated with atherosclerosis has not been previously addressed." (PMID 38790628, 2024). "Downregulated SSAO activity, protein, and mRNA expression due to downregulated LOX (as observed in our study) could accelerate further damage to the ECM stability, impairing vascular tone regulation and, consequently, posing a greater risk for the development of atherosclerosis." (PMID 36358914, 2022). "Conversely, in atherosclerosis-prone mice, osteoprotegerin (OPG) promoted VSMC accumulation, LOX upregulation, LOX-dependent collagen fiber maturation, and the formation of stable fibrous caps." (PMID 31615160, 2019). "Therapeutic interventions targeting LOX, such as β-aminopropionitrile (BAPN) and LOXL2-specific inhibitors like GSK2878163, have demonstrated efficacy in mitigating ECM cross-linking and decelerating atherosclerosis progression in animal models." (PMID 40661776, 2025). "Upregulated genes in BBA-derived VSMCs are related to arterial mineralization and atherosclerosis, such as PTX3, SPP1, LOX, etc., whereas vasodilation and physiological regulatory genes such as MGP, ACTA2, and MYL9 were conversely enriched in conventional IA-derived VSMCs." (PMID 35874788, 2022). "Additional studies are needed to further investigate the relationship between LOX and SSAO in rat aortic VSMCs, and to demonstrate how this might contribute to the development of atherosclerosis." (PMID 36358914, 2022). "Moreover, we have demonstrated LOX as a regulator of SSAO activity, VAP-1 protein and Aoc3 mRNA expression in early passage rat aortic VSMCs, highlighting SSAO as an important novel therapeutic target for the treatment/prevention of atherosclerosis." (PMID 36902376, 2023). "Thus, LOX plays an important role in the ECM, both intra- and extra-cellularly; in the dermis during normal physical development, aging, wound repair; and in fibrotic disorders including liver cirrhosis and atherosclerosis." (PMID 28036074, 2016).
heart failure (18 papers, 2013 to 2024). Inability of the heart to pump blood at an adequate rate to meet tissue metabolic requirements. "Our results suggest that COMP, COL8A1, LOX, and ACOT1 warrant further investigation in the development of cardiac fibrosis and as potential biomarkers for causing heart failure." (PMID 38854759, 2024). "For example, inhibition of LOX isoenzymes has shown to be of benefit in diminishing myocardial fibrosis in both volume- and pressure-overload murine models of heart failure." (PMID 37443910, 2023). "Torsemide corrected both lysyl oxidase overexpression and enhanced collagen cross-linking leading to normalization of LV chamber stiffness in patients with heart failure." (PMID 28428753, 2017). "Furthermore, a trial on heart-failure patients treated with the loop diuretic torasemide showed reduced myocardial LOX and collagen cross-linking and improved ejection fraction." (PMID 37443910, 2023). "Increased LOX expression in the vascular wall and within the atherosclerotic lesion stabilizes the plaque against rupture and subsequent MI, whereas increased LOX expression in the infarcted cardiac area promotes fibrosis and subsequent post-MI sequelae such as cardiac dysfunction and heart failure." (PMID 36292250, 2022). "Thus, an increased expression and activity of LOX has been demonstrated in the myocardium of patients with heart failure, as well as with dilated cardiomyopathy, which correlated with increased collagen content and collagen cross-linking." (PMID 32046347, 2020). "Moreover, both myocardial and serum miR-19b levels were found inversely correlated with expression levels of lysyl oxidase (LOX), collagen cross-linking and left ventricular stiffness in AS patients, particularly in patients with heart failure." (PMID 29026447, 2017). "Osteopontin-mediated myocardial fibrosis in heart failure: a role for lysyl oxidase?" (PMID 29930594, 2016). "While preventing the aberrant increase in LOX maturation may prevent the progression of hypotrophy to heart failure, the production of LOX from pro-LOX is not fully understood and may be dependent on a number of factors, complicating the development of therapies." (PMID 36970367, 2023). "Overexpression of lysine-specific demethylase 3A (KDM3A) leads to the up regulation of fibrosis-related genes COMP, COL8A1, and LOX and the down regulation of ACOT1, result in enhanced fibrosis and heart failure." (PMID 38854759, 2024). "Upregulated genes in Vehicle include NPPB, COL1A1, FMOD, LOX and MMP9, among others, some of which are related with pro-fibrotic processes and heart failure." (PMID 37342444, 2023).
Myocardial fibrosis (17 papers, 2016 to 2024). "Lysyl oxidase (LOX) is a copper-dependent extracellular enzyme, associated with myocardial fibrosis and cardiac dysfunction." (PMID 39502194, 2024). "Furthermore, T-cells are implicated in playing an important role in promoting myocardial fibrosis through the regulation of lysyl oxidase (LOX), a prominent collagen crosslinking enzyme." (PMID 35053159, 2021). "In this regard, we confirm these findings and expand the characterization of myocardial fibrosis in this model with novel data demonstrating that reduced NO bioavailability is associated with increased myocardial LOX expression and enhanced cross-linking of collagen fibrils." (PMID 28157237, 2017). "Altogether, the inhibition of myocardial fibrosis and LOX content are likely to explain the observed improvements in LV wall thickness and EDP after MIT and HIIT, possibly indicating their potential to limit myocardial wall stiffness." (PMID 37764732, 2023). "Emerging evidence suggests that the reciprocal modulation of Th17 and Treg on myocardial fibrosis was mediated by reciprocal regulation of LOX expression." (PMID 34880759, 2021). "In TNF-α-dependent myocardial fibrosis, however, LOX upregulation was noted and found to be due to TNF-α activation of TGF and PI3K signaling." (PMID 32708046, 2020). "LOX upregulation by TGF-β/Smad2/3 signaling was shown to promote myocardial fibrosis and chronic heart failure." (PMID 32708046, 2020). "A similar situation was reported in a model of chronic HF induced by aortic banding, in which the TGF-β1/Smad/AP-1-dependent induction of LOX aggravates myocardial fibrosis and HF." (PMID 31766500, 2019). "In the heart, AGEs exert detrimental effects by cross-linking ECM proteins in the presence or absence of LOX, thereby causing myocardial fibrosis and stiffening." (PMID 37764732, 2023). "Similarly, the induction of LOX by TGF-β1/Smad/AP-1 signaling exacerbates myocardial fibrosis and HF induced by abdominal aortic coarctation in rats." (PMID 31766500, 2019). "Indeed, the administration of β-aminopropionitrile (BAPN), an irreversible LOX inhibitor, to 38-week-old mice reversed established age-related myocardial fibrosis to a level similar to that of young mice." (PMID 31766500, 2019). "Research has demonstrated that IL-17 exacerbates myocardial fibrosis and heart failure by activating the ERK1/2-AP-1 pathway to induce LOX expression." (PMID 39502194, 2024). "In SHR, which showed a significant increase cardiac LOX and CCL accompanied by a rise in phosphorylated Smad2, CTGF, and collagen type I, a synthetic peptide from TGF-β1 type III receptor (P144) limits myocardial fibrosis." (PMID 31766500, 2019). "Furthermore, LOX inhibition by BAPN was shown to attenuate TGF-β-mediated downstream effects, including cardiac dysfunction, ventricular remodeling and myocardial fibrosis." (PMID 32708046, 2020). "In this regard, we report here that administration of EXP3179 completely prevented the excess of CTGF, LOX and CCL, and fully abrogated myocardial fibrosis, yet without normalization of BP." (PMID 28157237, 2017). "In contrast, we found that although administration of EXP3174 normalized BP, it failed to prevent myocardial CTGF and LOX overexpression, as well as the excess of CCL, and only partially reduced myocardial fibrosis." (PMID 28157237, 2017).
hepatocellular carcinoma (16 papers, 2016 to 2025). A malignant tumor that arises from hepatocytes. "Calcium channel α2δ1 subunit-positive hepatocellular carcinoma (HCC) TICs initiate ECM remodeling by secreting LOX, leading to the formation of abundant cross-linked collagen fibers around the tumor." (PMID 39239559, 2024). "In hepatocellular carcinoma, the FOXM1b transcription factor has been shown to directly bind to the LOX and LOXL2 genes promoters, thereby facilitating their expression." (PMID 39247609, 2024). "Despite this, a phase 1c/2a trial combining a lysyl oxidase pan inhibitor with standard of care (Atezolizumab plus Bevacizumab) in unresectable hepatocellular carcinoma will be underway in 2022." (PMID 35205728, 2022). "In contrast, this study uses a pan-lysyl oxidase inhibitor, which has successfully completed pre-clinical development, Phase 1 studies, and is currently in Phase 2 for myelofibrosis and hepatocellular carcinoma." (PMID 35628342, 2022). "In tumor tissues of hepatocellular carcinoma, upregulated LOX similarly correlated with increased VEGF and reduced overall survival related to increased tumor cell proliferation, migration and invasion." (PMID 32708046, 2020). "Elements of regulatory interactions involving LOX-mediated matrix stiffness were also revealed in hepatocellular carcinoma." (PMID 32708046, 2020). "A tissue microarray analysis of genes associated with increased stromal stiffness confirmed a relationship between elevated levels of LOX and COL1 expression involving integrin β1/GSK-3β/β-catenin signaling associated with hepatocellular carcinoma development and progression." (PMID 32708046, 2020). "Increased matrix stiffness induced the expression of LOX enzymes in hepatocellular carcinoma (HCC) cells growing on different stiffness substrates." (PMID 31130685, 2019). "In hepatocellular carcinoma (HCC), it is now well established that lysyl oxidase activity is significantly elevated in the tumors." (PMID 35205728, 2022). "In conclusion, there is positive coregulation of LOX and VEGF expression controlled by TGF-β in hepatocellular carcinoma cells and tumors that correlates with reduced overall survival." (PMID 32708046, 2020). "Positive correlation of LOX and VEGF expression levels, dose-dependent upregulation of both by TGF-β, and under siRNA LOX conditions, decreased VEGF and p38 MAP signaling were noted in hepatocellular carcinoma cells." (PMID 32708046, 2020). "FoxM1b, a transcription factor often overexpressed in human cancers, enhances LOX and LOXL2 expression by directly binding to the LOX and LOXL2 gene promoters, further activating the downstream AKT-Snail pathway and promoting EMT and hepatocellular carcinoma metastasis." (PMID 28036074, 2016).
aneurysm (14 papers, 2012 to 2025). Bulging or ballooning in an area of an artery secondary to arterial wall weakening. "Lowering LOX expression and activity in endothelial cells is associated with a high risk of aneurysms and vascular malformation." (PMID 35885053, 2022). "Importantly, mutations to the gene that encodes lysyl oxidase (LOX), which governs enzymatic cross-linking of collagen, result in aneurysms in humans and mice." (PMID 33079926, 2020). "In addition to understanding the role of elastase concentration, we also studied the impacts of LOX inhibition after aneurysm formation." (PMID 34997075, 2022). "While collagen has been proposed to increase aortic stiffness and predisposition to aneurysm and dissection, Busnadiego et al45 demonstrated that reduction of mature collagen deposition via lysyl oxidase enzyme blockade worsens aneurysm severity in a murine model." (PMID 31886938, 2020). "Interestingly, in two other experimental models of AAA in rodents, the elastase- and the CaCl2-induced AAA models, aneurysm development was accompanied by a reduction of LOX expression and activity." (PMID 31615160, 2019). "LOX knockout mice are prone to thoracic aortic aneurysm and dissection and die soon after birth, with a 60% reduction in elastin crosslinks observed in aortic tissue, underscoring LOX inactivation as a key prognostic indicator for aneurysm and dissection prognosis." (PMID 31214600, 2019). "Further, by altering the timeline of BAPN application, we show that, while initial elastase degradation strongly influences final aneurysm size and presence of ILT, LOX inhibition also remains necessary for continued aneurysm expansion." (PMID 34997075, 2022). "For example, rat pups weaned from their mothers and fed the general LOX/LOXL inhibitor, β-aminopropionitrile (β-APN), form aneurysms." (PMID 26968815, 2016). "Indeed, periadventitial LOX inhibition with BAPN-loaded nanofibers improved AVF dilation over 3 weeks and led to adaptive remodeling using a much smaller dose (142.5 μg) than aneurysm and dissection models which typically co-administer BAPN with angiotensin II or elastase." (PMID 36926045, 2023).